KRT18 (keratin 18)
Diseases named in the same sentence as KRT18 in open-access papers (continued):
Sharing a sentence is not in itself a finding about the gene and the disease.
cancer (continued). "We then checked the expression of the canonical cell-type markers: cancer/epithelial cell marker genes (Cdh1, Krt18, and Krt5); mesenchymal cell marker genes (Col1a1, Col1a2, and Col3a1); immune cell marker genes (Ptprc, Cd68, and Csf1r); and endothelial cell marker genes (Pecam1, Emcn, and Cdh5)." (PMID 34497807, 2021). "Cytokeratin 18 (CK18) is an intermediate filament protein of the cytokeratin acidic type I group and is primarily expressed in single-layered or “simple” epithelial tissues and carcinomas of different origin." (PMID 33588765, 2021). "Our results showed that honokiol can exert its anti-cancer effect by binding to KRT18." (PMID 33330500, 2020). "The authors also elaborated an immunofluorescence-based assay using a cocktail of monoclonal antibodies targeting cytokeratin (CK) 8 and cytokeratin 18 to specifically identify cancer cells, since both CK8/CK18 are nearly present in all tumors of epithelial origin." (PMID 32486365, 2020). "Cytokeratin 18(CK18) is widely expressed in many different organs and cancers." (PMID 31598152, 2019). "Generally, KRT18 is overexpressed in most types of human cancer." (PMID 31345960, 2019). "The presence of W256 cancer cells in longitudinal sections of the ipsilateral tibiae from rats given these cells by unilateral ITI was confirmed by immunohistochemical staining using the anti-Cytokeratin 18 antibody [C04] (Alexa Fluor® 488) ab187573 (Abcam)." (PMID 28729837, 2017). "We show that CDK11p58-induced SPDEF degradation reduces expression of the epithelial-specific genes E-cadherin and cytokeratin 18 indicating the CDK11p58-SPDEF axis may play an important role in cancer cell migration and invasion." (PMID 26885618, 2016). "Taken together, our results suggest that OC inhibits metastasis through the induction of the expression of keratin 18 and may be useful in cancer therapy." (PMID 25973684, 2015). "Furthermore, the knockdown of keratin 18 by small interfering RNAs inhibited the expression of tubulin and increased the metastasis of cancer cells, suggesting that keratin 18 is the upstream signal of tubulin and plays a vital role in metastasis." (PMID 25973684, 2015). "Taken together, these results indicated the existence of an inverse correlation between the expression of keratin 18 and metastasis, suggesting that keratin 18 may play a pivotal role in cancer cell metastasis." (PMID 25973684, 2015). "Keratin 18 (K18) was identified as the most possible keratin molecule involved in the regulation of β1 integrin recycling by immunofluorescence colocalization observation in HeLa cells and different types of cancer tissues." (PMID 25537517, 2015). "Bipotent precursor cells present in mammary stem/progenitor cells and breast TICs/cancer stem cells have been characterized by coexpression of luminal epithelial cytokeratin 18 (K18)/K8 markers and myoepithelial cytokeratin 14 (K14)/α-smooth muscle actin (SMA) markers." (PMID 23300950, 2013). "Luminal-like cancers showed an enrichment of luminal lineage markers (e.g., NKX3.1 and KRT18), whereas basal-like cancers showed enrichment of the basal lineage CD49f signature." (PMID 41590381, 2026). "The expression of KRT18 (p < 0.0001) and OLFM4 (p = 0.0435) in the cancer‐pre subcluster was significantly greater than that in the other subclusters." (PMID 40860436, 2025). "While this observation requires cautious interpretation, it is worth noting that other epithelial markers such as KRT18 showed strong expression in HCC, similar to other cancer types." (PMID 41228323, 2025). "Several KRT genes, including the phylogenetically older KRT8, KRT18, KRT19, KRT23, KRT79, KRT80 and KRT222, were found to be differentially expressed in diverse types of cancers." (PMID 36949761, 2023). "We detected cancer cells using markers typical of LUAD and alveolar epithelium (EPCAM, CDH1, KRT19, KRT18, KRT8)." (PMID 37745301, 2023).
cancer (continued). "Alterations in the levels of some proteins in the COS–GA group, such as HSPA9, HIST2H2BF, keratin 18, HINT1, and vimentin, were proposed as anti-cancer mechanisms in this study." (PMID 37371778, 2023). "Several members of the KRT gene family, including the evolutionarily older KRT8, KRT18, KRT19, KRT23, KRT79, KRT80 and KRT222, were shown to be differentially regulated in diverse cancer types." (PMID 36949761, 2023). "We further examined the metastatic ratio via immunostaining for cytokeratin 18 (CK‐18), a specific marker for MGC‐803 cells, and cancer cells." (PMID 37409440, 2023). "Anti-cancer-activity-related proteins were altered, including CLTA, HSPA9, HIST2H2BF, KRT18, HINT1, DSP, and VIM." (PMID 37371778, 2023). "Among these three cell types, HPCs population contained mainly cancer cells, as KRT8 and KRT18 were the marker genes of epithelial cells." (PMID 37517066, 2023). "This technique identified cell clusters that, through marker genes, included cancer cells—markers EpCAM, KRT8, KRT18, and KRT23, fibroblasts—marker COL1A1 (cancer cells, 4389 cells; fibroblasts, 2549 cells)." (PMID 34026600, 2021). "KRT7, KRT18, KRT19 protein expression in tumors were reported to predict prognosis in several cancer types." (PMID 34070214, 2021). "Recently, single‐cell analysis of the transcriptome and epigenome also showed that KRT8, KRT18, CLDN4, KRT19, KRT20, etc. are highly expressed in CRCs,[12a] consistent with our results that these genes were highly expressed in cancer EPCs." (PMID 33898197, 2021). "Conversely, HDAC1, CCDN1, PCNA, CDX1, KRT18, CDX2 and CASP3 are all expressed at significantly lower levels in normal tissue compared to adenomatous polyp or carcinoma tissues." (PMID 25423035, 2014). "The M30 antibody detects a caspase-degraded product, CK18-Asp396, of the important cytoskeletal protein cytokeratin 18 (CK18) of epithelial cells, which is expressed by most carcinomas, including those of breast, prostate, lung and colon." (PMID 19302716, 2009). "The epithelial and cancer cells showed higher KRT8, KRT18, KRT19 and ANXA4 expression." (PMID 39149248, 2024). "However, six proteins influenced cancer cell survival in the COS–GA group in previous studies, with downregulated HSPA9 and HIST2H2BF and upregulated KRT18, HINT1, DSP, and VIM proteins." (PMID 37371778, 2023). "Furthermore, cytokeratin 18 (CK18) and pyruvate kinase (PKM) were identified in simple carcinoma cells." (PMID 37893211, 2023). "YKL-40 gene expression was primarily increased in the fibroblast (gene annotation: COL1A, BGN, DCN), myeloid (gene annotation: CD68, LYZ, AIF1), cancer (gene annotation: EPCAM, KRT7, KRT18), and B-cell (gene annotation: CD79A, CD79B) populations in cancer tissue compared to healthy tissue." (PMID 35631632, 2022). "Conversely, LINC02470 and SMAD3 were expressed at lower levels in low-grade cancer cells or nontumor cells with higher epithelial-like traits, such as higher E-cadherin and cytokeratin 18 expression but lower N-cadherin and vimentin expression." (PMID 35205713, 2022). "M30 is suitable for apoptosis detection in cancer cells because cytokeratin-18 is expressed in epithelial cells and apoptosis in non-epithelial cells including stromal cells can be excluded by M30." (PMID 30813476, 2019). "In our LBC samples, however, CD44high/CD24low cells accounted for an average of 60% of all cancer cells and were positive for cytokeratin 18, a marker for differentiated luminal cells (data not shown)." (PMID 19583841, 2009). "Notably, the expression levels of normal pancreatic epithelial cell markers, SST and INS, were specifically higher compared to cancer cells, suggesting the normal functions of these cells, while malignant marker genes, SOX9 and KRT18, were remarkably upregulated in cancer cells." (PMID 35941362, 2022).
cancer (continued). "Indeed, we have not obtained any data indicating a correlation between KRT18 expression level and AZM-induced growth inhibition in several cancer cell lines used in this study (data not shown)." (PMID 36871041, 2023).
adenocarcinoma (23 papers, 2004 to 2025). A common cancer characterized by the presence of malignant glandular cells. "Similarly, with paired samples of normal colon mucosa and adenocarcinomas derived from 27 patients, proteomic analysis revealed that keratin 18 was at a significantly lower level in the normal mucosa compared with the tumor tissue." (PMID 15748282, 2005). "For example, keratins KRT8, KRT18, and KRT19 are expressed in most adenocarcinomas." (PMID 35267493, 2022).
respiratory disease (7 papers, 2020 to 2024). "We and others have reported that transgenic mice expressing the human angiotensin-converting enzyme 2 (hACE2) viral receptor under the control of the Keratin 18 (K18) promoter develop severe and lethal respiratory disease subsequent to SARS-CoV-2 intranasal challenge." (PMID 33961540, 2021).
Cardiovascular Disease (3 papers, 2023 to 2024). "We aimed to explore the discriminant accuracy of Cytokeratin 18 (CK18, including M65 and M30 forms) for an elevated fatty liver index (FLI) as a validated proxy of NAFLD, and cardiovascular disease (CVD) risk in the general population." (PMID 37509164, 2023).
heart disease (2 papers, 2021 to 2024). "Further potentially disease-relevant protein candidates without a known functional relation to hypertrophy, fibrosis or decompensated heart disease were SLTM, HNRNPLL, FIP1L1, RNMT, KRT18 and PUF60 and the downregulated NUDT4, GCAT, KIDINS220 and ARVCF." (PMID 34937869, 2021).
immune disorders (2 papers, 2025). "We used transgenic mice expressing the human angiotensin I-converting enzyme 2 (ACE2) receptor driven by the cytokeratin-18 (K18) gene promoter (K18-hACE2), shown to be a model that mimics the clinical manifestations and immune disorders of severe COVID-19 infection in humans." (PMID 39814955, 2025).
KRT18 also shares sentences with these, for which no sentence is quoted: pneumonia (23 papers); encephalitis (15); lung disease (14); esophageal squamous cell carcinoma (9); tauopathies (8); renal cell carcinoma (6); type 2 diabetes (6); Anosmia (5); cholangiocarcinoma (5); inflammation (5); serous ovarian cancer (5); vasculitis (5); autoimmune hepatitis (4); breast invasive carcinoma (4); chronic hepatitis B (4); hepatitis C (4); metabolic disorders (4); neurodegenerative disease (4); oral squamous cell carcinoma (4); acute GVHD (3); acute respiratory distress syndrome (3); colitis (3); End Stage Liver Disease (3); frontotemporal dementia (3); gastrointestinal tumor (3); heart failure (3); hepatitis B (3); Hypertension (3); influenza (3); Kidney Disease (3).
A further 183 diseases each share a sentence with KRT18 in 3 papers or fewer.